INS (insulin)
Diseases named in the same sentence as INS in open-access papers (continued):
Sharing a sentence is not in itself a finding about the gene and the disease.
type 2 diabetes (continued). "Although incretin therapy is clinically available in patients with type 2 diabetes undergoing hemodialysis, no study has yet examined whether incretin therapy is capable of maintaining glycemic control in this group of patients when switched from insulin therapy." (PMID 23445717, 2013). "Previous studies have shown significant positive correlations between chemerin levels and fasting blood glucose, fasting insulin, HOMA-IR, HbA1c, independent of age and BMI were observed in subjects with type II diabetes compared to normal glycemic subjects." (PMID 23468920, 2013). "Among participants without type 2 diabetes, HOMA-IR and fasting serum insulin concentrations increased across fetuin-A quartiles after adjustment for age, sex, community, current smoking, current drinking, BMI (both p for trend <0.0001)." (PMID 21556362, 2011). "Type 2 diabetes and GDM have similarities: both are characterized by a strong family history, overweight, insulin resistance, and lack of compensatory pancreatic insulin secretion in demanding hormonal circumstances." (PMID 21429234, 2011). "In obese humans, food intake (including 60% of carbohydrates) with postprandially increased insulin response fails to suppress ghrelin levels sufficiently, suggesting that ghrelin may be involved in some of the multiple pathophysiological mechanisms leading to obesity and type 2 diabetes." (PMID 21949667, 2011). "In individuals with type 2 diabetes, a combination of oral antidiabetic drugs (OAD) and basal insulin is commonly initiated after OAD treatment has failed to achieve sufficient metabolic control." (PMID 20415692, 2010). "The impact of the high glucose-induced increase in miR-133a on insulin biosynthesis rates was not dramatic, but this mechanism may act in synergy with other high glucose-induced suppressive mechanisms leading to beta-cell failure and aggravation of Type 2 diabetes." (PMID 20520763, 2010). "Interestingly, this improvement of glycemic control was not due to enhanced insulin sensitivity but rather due to improved β-cell secretory function suggesting that IL-1 is more involved in maintaining β-cell homeostasis than in adipose tissue biology in human subjects with type 2 diabetes." (PMID 21179199, 2010). "However, to our knowledge, there are no studies on the relationship between insulin secretory capacity and TIR in type 2 diabetes." (PMID 38839813, 2024). "While we observed a reduced early insulin response in non-obese, healthy subjects after 36 h of fasting as compared to 12 h, this finding persisted in obese people only in the IVGTT and disappeared completely in those with type 2 diabetes." (PMID 36771218, 2023). "Daily consumption of a ripe avocado did not alter insulin sensitivity or glycaemic outcomes in response to an OGTT after 12 weeks of intervention in adults with overweight/obesity or after 4 weeks in patients with type 2 diabetes." (PMID 38004206, 2023). "The strength of this study was that it was a multicenter study, and only required type 2 diabetes with insulin-treated and non-insulin-treated to have at least three FCG and three PCG measurements, indicating that this study had good extrapolation in type 2 diabetes." (PMID 36824358, 2023). "A diet containing baicalein (250 and 500 mg/kg/day) administered to mice with non-genetic type 2 diabetes fed with a high-fat diet (HFD) led to a significant amelioration of glucose tolerance, hyperglycemia, and blood insulin levels compared to the control group." (PMID 36902160, 2023). "Studying participants with and without type 2 diabetes, a standardized liquid MMTT was previously shown to effectively interrogate multiple metabolic parameters, including postprandial blood insulin, glucose, TGs, adipose lipolysis, amino acid metabolism, and more." (PMID 35634390, 2022).
type 2 diabetes (continued). "Apart from further studies on CGM, it will also be worthwhile to consider levels of the islet autoantibodies, in particular ZnT8A, other non-HLA genetic factors, measures of insulin sensitivity such as HOMA-IR along with BMI and family history of type 2 diabetes." (PMID 34983671, 2022). "Twelve-week oral administration of BPS improved insulin sensitivity without altering body weight, BMI, waist circumference or lipid profile in human patients with type 2 diabetes, suggesting PGI2 supplementation improves insulin sensitivity without improving AT function." (PMID 35557517, 2022). "While the ADA recommends the use of CGM in adults taking multiple daily injections or continuous insulin infusion, and states that CGM can be used in adults on basal insulin, CGM is not specifically recommended for use in older adults with type 2 diabetes taking insulin." (PMID 36694891, 2022). "Furthermore, α-Spinasterol enhanced insulin secretion in response to high glucose concentrations, with no toxic effects on INS-1 cells; this effect was superior to that demonstrated by gliclazide (positive control), commonly prescribed to treat type 2 diabetes (T2D)." (PMID 35270128, 2022). "Taken together, our results using two complementary AIS markers, AnkyrinG and βIV spectrin, indicate that increase of methylglyoxal, but not insulin resistance or high glucose alone, could be the key initiator of AIS shortening during type 2 diabetes." (PMID 34531281, 2021). "In the INSUPAR trial, previously published by our group, we assessed two insulin regimens in adult inpatients with type 2 diabetes in a non-critical setting with indication for total parenteral nutrition (TPN; subcutaneously administered glargine insulin vs. regular insulin inside the TPN bag)." (PMID 32471262, 2020). "Therefore, we investigated whether improvements in insulin sensitivity, metabolic flexibility, body composition, aerobic fitness and muscle strength are limited by a FH+ following eight weeks of combined exercise training compared to individuals without a family history of type 2 diabetes (FH–)." (PMID 32231642, 2020). "Although MAPK insulin signalling pathway was not investigated in this study, previous data from researchers support the idea that alterations in MAPK signal transduction contributes to development of Type II diabetes as well." (PMID 32670384, 2020). "Univariate analyses of the associations between AUCsRAGE 0–240 and AUC0–240 for glucose and the glucose regulating hormones insulin, glucagon, GLP-1, and GIP showed strong negative relationships between sRAGE and GLP-1 in individuals with type 2 diabetes, both during OGTT and IIGI at the 75 g dose." (PMID 32987824, 2020). "Additionally, the modulatory effects of insulin and caloric intake on MCP-1 levels were mainly examined in either healthy obese or noncritically ill patients with type 2 diabetes rather than in the ICU setting." (PMID 31052277, 2019). "Despite its anti-obesity effect, INT-767 fails to reverse diet-induced glucose intolerance or insulin insensitivity, suggesting that INT-767 may not be useful for treatment of type II diabetes." (PMID 29361497, 2018). "Therefore, the shape of the association of FPG and HbA1c with incident type 2 diabetes is non-linear, while the shape of 2hPG, loge fasting insulin and loge HOMA-IR with incident type 2 diabetes is linear." (PMID 29018885, 2018). "We previously reported that OLETF rats have the features of type 2 diabetes at 25 weeks of age; the abnormal glucose tolerance in the OLETF rats may be due to insulin resistance because no impairment of insulin secretion was observed." (PMID 29447298, 2018). "Since in insulin resistant conditions insulin is not able to suppress gluconeogenesis, the inhibition of G6pase and PEPCK by BITC might be considered positive in type 2 diabetes prevention and treatment." (PMID 27622707, 2016).
type 2 diabetes (continued). "We analyzed (a) insulin sensitivity (IS), (b) plasma insulin (PI), and (c) plasminogen activator inhibitor-1 (PAI-1) in type 2 diabetes (T2D) patients with (group A) and without (group B) atherothrombotic ischemic stroke (ATIS), nondiabetics with ATIS (group C), and healthy controls (group D)." (PMID 26089903, 2015). "While other studies have used an MMTT to evaluate glucose and insulin responses in adults with and without type 2 diabetes, to our knowledge, ours is the first that has assessed whether responses to an MMTT as predictors of type 2 diabetes." (PMID 38987291, 2024). "Finally, to assess the potential therapeutic benefit of counteracting AMPK signaling deficit in GBS, we compared the disease severity in GBS patients with type 2 diabetes treated with AMPK activator metformin and those receiving insulin and/or sulphonylurea derivatives without metformin." (PMID 36139470, 2022). "Given Hispanic and non-Hispanic Black children and adolescents have been reported to have higher fasting insulin, HOMA-IR levels, and type 2 diabetes prevalence than their non-Hispanic White counterparts, targeting increased breakfast consumption in these populations could mitigate risk." (PMID 35684120, 2022). "ADF did not change insulin response in the patients with type 2 diabetes, but the subset of patients that had an IVGTT perfomed after ADF + WL (T2DM, n = 6) displayed improved (p < 0.0001) insulin response, compared with baseline and with ADF." (PMID 36531168, 2022). "Interestingly, it has been observed that islet cells from human donors with Type 2 diabetes showed a significant (80–90%) reduction in GLUT-2 expression and lacked the glucose-stimulated insulin secretion (GSIS) response, a marker of beta cell dysfunction in Type 2 diabetes." (PMID 34639123, 2021). "However, indices which require measurement of insulin (or C-peptide) levels, such as HOMA-IR, are not suitable for estimating insulin sensitivity in an unselected population of individuals with type 2 diabetes including a large proportion (~ 25) of insulin-treated patients such as the RIACE cohort." (PMID 33715620, 2021). "Unlike improvements in insulin signaling that may be compromised with obesity, training-induced increases in GLUT4 have been reported in older, obese individuals, as well as older men with type 2 diabetes." (PMID 31684154, 2019). "Moreover, most of the studies examining the effects of caloric intake and insulin on inflammation have been conducted in non-ICU settings with more controlled homogenous subjects, either healthy obese or non-critically ill patients with type 2 diabetes." (PMID 31052277, 2019). "Consequently, it is speculated that antidiabetic treatments might, at least in part, lead to this obscure or nonsignificant relationship between blood glucose, insulin resistance and ANGPTL8 in type 2 diabetes." (PMID 30007407, 2018). "However, according to our study which showed that the mean BD/TDD ratio of Chinese type 2 diabetic patients receiving BBT was 0.23, those ratios might not match the real need of insulin therapy in Chinese type 2 diabetic patients." (PMID 22720003, 2012). "SGLT2i are now recommended for patients with type 2 diabetes mellitus (T2DM) and showed glycemic and non-glycemic benefits in T1DM as well, including improved glycemic control and glycemic variability, decreased insulin dose requirement, and blood pressure and body weight reduction." (PMID 33373368, 2020). "Interestingly, insulin sensitivity consistently improved in type 2 diabetic patients as well as in obese non-diabetic subjects following long-term exercise, indicating that IMCL and the flexibility of IMCL are not the only factors that determine insulin sensitivity." (PMID 27649157, 2016).
type 2 diabetes (continued). "T1D–type 1 diabetes; T2D–type 2 diabetes; GAD-65 A–glutamic acid decarboxylase-65 autoantibodies; IA2—anti-islet antigen phosphatase; anti- ZnT8—zinc transporter 8; IAA–antibodies against insulin–no data; M–male; F–female; DKA–diabetic ketoacidosis; NOD–new onset diabetes." (PMID 35769263, 2022).
Obesity (13,958 papers, 2000 to 2026). Accumulation of substantial excess body fat. "Semaglutide addresses a broader spectrum of systemic risk factors for DR than insulin, including hypertension, dyslipidemia, chronic kidney disease, and obesity." (PMID 41851808, 2026). "Common human metabolic disorders are associated with increased cellular senescence in key insulin-regulated target cells, even after adjusting for the contributing effect of aging and BMI/obesity." (PMID 41189469, 2026). "A similar pattern emerged for obesity-related cancers: surgery was associated with lower rates in the two highest insulin thirds (HRadj = 0.52; 95% CI [0.37, 0.73]; p < 0.001, and HRadj = 0.66; 95% CI [0.49, 0.88]; p = 0.006)." (PMID 41490246, 2026). "Obesity represents a heterogeneous metabolic disorder characterized by substantial interindividual variation in inflammatory status, insulin sensitivity, and cardiometabolic risk." (PMID 41901191, 2026). "Bariatric surgery is associated with a lower risk of cancer and cancer-related mortality in women with obesity, with the strongest association observed for female-specific cancers in women with elevated baseline insulin levels." (PMID 41490246, 2026). "Classically, endocrine islet beta (β) cell secretion of insulin is thought to promote the development of obesity-associated pancreatic adenocarcinoma (PDAC), an exocrine cell-derived tumor." (PMID 41760660, 2026). "This, in turn, stimulates the production of vascular endothelial growth factor (VEGF), which promotes vascular endothelial genesis and has been associated with improved insulin sensitivity in hypoxic training for adults with obesity." (PMID 41250924, 2026). "Dysregulation of specific RBPs has been implicated in obesity and metabolic disorders, with several shown to affect adipogenesis, lipid handling, thermogenesis, and insulin sensitivity across different adipose depots." (PMID 41596407, 2026). "Obesity is strongly linked to insulin resistance, affecting metabolic organs and interfering with insulin signalling." (PMID 41543809, 2026). "Insulin therapy is the standard treatment for type 1 diabetes (T1D), but people with T1D can also develop obesity and metabolic risk markers." (PMID 41048008, 2026). "Obesity-associated asthma is a heterogeneous condition shaped by underlying metabolic dysfunctions such as insulin resistance and altered inflammatory processes." (PMID 41567689, 2026). "Background/Objectives: Obesity is a complex metabolic disorder associated with chronic low-grade inflammation, insulin resistance, and increased risk of metabolic complications." (PMID 42196825, 2026). "Higher HbA1c levels, lower insulin sensitivity, and obesity are linked to renal hyperfiltration, even at prediabetes stages." (PMID 40762952, 2025). "Obesity is associated with altered myokine secretion, ectopic fat accumulation, and low-grade chronic inflammation—all of which impair glucose uptake and insulin action." (PMID 40722647, 2025). "Obesity heightens the risk of pancreatic cancer by contributing to insulin resistance and higher circulating levels of insulin, which are then associated with the development of tumors in the pancreas." (PMID 41041606, 2025). "Such interventions include dietary modifications, increased physical activity, and lifestyle changes, which not only address the underlying behavioral causes of obesity but also improve insulin sensitivity." (PMID 39857741, 2025). "Overall, these studies suggest that KLK7 is involved in the metabolic dysfunctions associated with obesity, particularly in terms of insulin action." (PMID 40427653, 2025). "Although leptin has clearly been effective in inducing weight loss and improving insulin sensitivity in leptin-deficient individuals, the same has not been observed in those with leptin excess in lifestyle-related obesity." (PMID 40214973, 2025).
Obesity (continued). "Obesity is frequently associated with high blood insulin concentrations, which are also associated with hyperactivation of intracellular transduction pathways." (PMID 40385289, 2025). "These include two clusters linked to insulin secretion and action, and one associated with obesity and dyslipidaemia." (PMID 40088285, 2025). "Some anti-obesity drugs also improve glycemic control, while many antidiabetic medications—especially insulin—can cause weight gain, complicating disease management." (PMID 40565464, 2025). "This is caused by the relatively reduced insulin-sensitive lipoprotein lipase activity in obesity, which leads to a decrease in HDL-C." (PMID 39981087, 2025). "Although its exact role has not yet been fully demonstrated, it is known that it is widely effective in ameliorating obesity-associated insulin sensitivity by directly or indirectly modulating the local concentration of short-chain fatty acids [SCFAs]." (PMID 40077722, 2025). "In BCATm−/− animal models, elevated circulating BCAA levels were associated with beneficial phenotypes, such as reduced obesity and increased insulin sensitivity." (PMID 40036545, 2025). "Obesity can cause impaired glucose and insulin tolerance in mice, and 10 weeks of aerobic exercise intervention cannot restore glucose tolerance and insulin tolerance." (PMID 41278194, 2025). "Low ADP concentrations and an altered ratio between leptin and ADP are associated with obesity, altered insulin signaling, and an inflammatory state in obese patients." (PMID 40137085, 2025). "Pivotally, Australia is facing an obesity epidemic, and as a growth hormone, it is crucial to acknowledge that insulin hinders weight loss efforts." (PMID 39511718, 2025). "Metabolic and biosynthetic processes were enriched in differential gene expression analysis, with maternal obesity associated with downregulation of insulin-dependent energy-sensing pathways (PI3K, AMPK) in uMSC adipocytes." (PMID 41154332, 2025). "Secondly, a high level of free fatty acids in individuals with obesity increases TG storage in the muscle and liver, reduces insulin sensitivity, and causes lipotoxic responses." (PMID 40190401, 2025). "Evidence suggests that interrupting the inflammatory response caused by obesity enables the recovery of insulin sensitivity." (PMID 41300428, 2025). "A higher HOMA-IR indicates reduced insulin responsiveness and is commonly associated with obesity, sedentary behavior, and dyslipidemia." (PMID 40988275, 2025). "An increased F/B ratio is commonly linked to obesity or metabolic disorders, potentially due to enhanced caloric extraction from food, fat deposition, lipogenesis, or impaired insulin sensitivity." (PMID 40375894, 2025). "MASLD is commonly associated with obesity and metabolic disturbances, leading to increased systemic inflammation and impaired insulin signaling, thus promoting the development of various metabolic diseases, including MASH and T2DM26." (PMID 41413106, 2025). "Asians have higher insulin sensitivity but lower insulin secretion than Caucasians8), predisposing them to T2D at lower obesity levels." (PMID 40666490, 2025). "A. muciniphila has also been associated with the prevention of obesity, including reduced adiposity and increased insulin sensitivity." (PMID 39940420, 2025). "In females, metabolic abnormalities such as obesity and elevated insulin and leptin are associated with acyclicity." (PMID 40646763, 2025). "In the context of obesity, IL-6 is intricately associated with chronic inflammatory processes and contributes to the inhibition of hepatic insulin signaling through the induction of SOCS3 protein expression." (PMID 40519917, 2025). "High glucose levels in obesity, such as FFAs, negatively impact β-cell function, causing glucotoxicity, ER stress, insulin production inhibition, and irreversible β-cell death via TXNIP pathway apoptosis." (PMID 40141412, 2025).